SMPDL3B (sphingomyelin phosphodiesterase acid like 3B)
Description:
Lipid-modulating phosphodiesterase. Active on the surface of macrophages and dendritic cells and strongly influences macrophage lipid composition and membrane fluidity. Acts as a negative regulator of Toll-like receptor signaling (By similarity). Has in vitro phosphodiesterase activity, but the physiological substrate is unknown. Lacks activity with phosphocholine-containing lipids, but can cleave CDP-choline, and can release phosphate from ATP and ADP (in vitro) (By similarity).
Synonyms: ASML3B
Tractability: Antibody: UniProt places it where antibodies can reach, with medium confidence; UniProt predicts a signal peptide or a membrane-spanning region; its Gene Ontology location is reachable by antibodies, with medium confidence. PROTAC: its protein half-life has been measured.
Gene: Protein-coding gene on chromosome 1 (27,935,000 to 27,959,157, forward strand). Ensembl gene ENSG00000130768.
Subcellular location: Secreted; Cell membrane
Subcellular location (Human Protein Atlas): Cytosol; Golgi apparatus; Predicted to be secreted
Gene Ontology:
Molecular function: phosphoric diester hydrolase activity; zinc ion binding; hydrolase activity; sphingomyelin phosphodiesterase activity
Biological process: lipid catabolic process; negative regulation of inflammatory response; negative regulation of toll-like receptor signaling pathway; sphingomyelin catabolic process
Cellular component: extracellular exosome; extracellular region; plasma membrane
Genetic constraint (gnomAD): Loss-of-function variants: 29 observed, 38.44 expected, observed/expected ratio (o/e) 0.75, 90% interval 0.56 to 1.03. The upper end of that interval is the gene's LOEUF score, 1.03, which puts it in group 4 of 6, group 1 being the genes least tolerant of losing a copy. Missense variants: 524 observed, 625.89 expected, observed/expected ratio (o/e) 0.84, 90% interval 0.78 to 0.9. Synonymous variants: 235 observed, 253.44 expected, observed/expected ratio (o/e) 0.93, 90% interval 0.83 to 1.03.
Homologues: Orthologues: chimpanzee SMPDL3B (99% identical), dog SMPDL3B (81% identical), pig SMPDL3B (78% identical), mouse Smpdl3b (75% identical), guinea pig SMPDL3B (74% identical), rabbit SMPDL3B (74% identical), rat Smpdl3b (74% identical), zebrafish smpdl3b (53% identical), tropical clawed frog smpdl3b (47% identical), Drosophila melanogaster CG32052 (36% identical), Caenorhabditis elegans ZK856.5 (34% identical). Paralogues in human: SMPDL3A (37% identical), SMPD1 (28% identical).
Diseases named in the same sentence as SMPDL3B in open-access papers:
SMPDL3B is named in the same sentence as 38 diseases in open-access papers, as found by Europe PMC text mining. Sharing a sentence is not in itself a finding about the gene and the disease. The quoted sentences say what the papers report.
diabetic kidney disease (8 papers, 2015 to 2025). Progressive kidney disorder caused by vascular damage to the glomerular capillaries, in patients with diabetes mellitus. "In models of diabetic kidney disease, excessive SMPDL3B expression impairs ceramide-1-phosphate synthesis and insulin receptor signaling, accelerating podocyte injury and glomerular decline." (PMID 41009450, 2025). "In this context, the sphingomyelinase phosphodiesterase acid-like 3b (SMPDL3b) enzyme was found to play a pertinent role in focal segmental glomerulosclerosis and diabetic nephropathy, where SMPDL3b was found to mediate insulin receptor signaling." (PMID 34660640, 2021). "Interestingly podocyte specific SMPDL3b deletion increases C1P levels and protects db/db mice from diabetic kidney disease." (PMID 34319011, 2021). "Here we report that SMPDL3b excess, as observed in podocytes in diabetic kidney disease (DKD), impairs insulin receptor isoform B-dependent pro-survival insulin signaling by interfering with insulin receptor isoforms binding to caveolin-1 in the PM." (PMID 31217420, 2019). "Thus, the SMPDL3B expression rate in vitro and in vivo correlates with podocyte damage in diabetic kidney disease (DKD)." (PMID 32575490, 2020). "FSGS and DKD (diabetic kidney disease) have elevated levels of circulating soluble urokinase plasminogen activator receptor (suPAR) but the podocyte expression of acid sphingomyelinase-like phosphodiesterase 3b (SMPDL3b) is elevated only in DKD." (PMID 25755650, 2015).
focal segmental glomerulosclerosis (6 papers, 2014 to 2025). A renal disorder characterized by sclerotic lesions in the glomeruli. "A recent study reported that the loss of sphingomyelin phosphodiesterase acid-like 3b (SMPDL-3b) in allogeneic human kidney grafts was related to the development of posttransplant proteinuria in patients with focal segmental glomerulosclerosis (FSGS)." (PMID 29687010, 2018). "Similarly, SMPDL3B dysregulation has been implicated in Alport syndrome and focal segmental glomerulosclerosis." (PMID 41009450, 2025). "As already evoked in the introduction, its off-target binding to the sphingomyelin-phosphodiesterase-acid-like-3b (SMPDL-3b) confers efficiency in the treatment of focal segmental glomerulosclerosis (FSGS), including multi-drug-resistant forms." (PMID 36077163, 2022). "It has been reported that the enzyme involved in the conversion of sphingomyelinase to ceramide, SMPDL3b, was decreased in renal biopsy samples of patients with focal segmental glomerulosclerosis (FSGS)." (PMID 26545114, 2015). "Acid sphingomyelinase-like phosphodiesterase 3b (SMPDL-3b) plays a role in the conversion of sphingomyelin to ceramide by acid sphingomyelinase (ASMase) and its levels are reduced in renal biopsy specimens from patients with recurrent focal segmental glomerulosclerosis (FSGS)." (PMID 27422620, 2017). "This is important as aSML3a (gene name: SMPDL3A) and aSML3b (gene name: SMPDL3B) have recently been identified as necessary for cell division and a potential target for treatment of the common kidney disease Focal Segmental Glomerulosclerosis (FSGS), respectively." (PMID 25144372, 2014).
acute myeloid leukemia (3 papers, 2021 to 2025). Acute myeloid leukemia (AML) is a group of neoplasms arising from precursor cells committed to the myeloid cell-line differentiation. "SMPDL3B has been proposed as a possible therapeutic target and an efficient predictive biomarker for acute myeloid leukemia (AML)." (PMID 38813495, 2023). "Particularly, the SMPDL3B correlated genes were also enriched in acute myeloid leukemia, hematopoietic cell lineage, and leukocyte trans-endothelial migration." (PMID 34504869, 2021). "SMPDL3B (sphingomyelin phosphodiesterase acid-like 3B) supports sphingolipid remodeling and has functional evidence for roles in motility/proliferation in prostate, acute myeloid leukemia, and ovarian cancer." (PMID 41411367, 2025).
hepatocellular carcinoma (3 papers, 2020 to 2023). A malignant tumor that arises from hepatocytes. "SMPDL3b expression has also been found in pancreatic zymogen granules, in plasma protein-depleted cerebrospinal fluid, in saliva exosomes, in human milk, liver, and hepatocellular carcinoma, suggesting a diverse function of SMPDL3b in different tissues and organs." (PMID 32914148, 2020). "ACER2 was reported to be overexpressed in hepatocellular carcinoma (HCC) tissue and to induce growth, invasion, and migration in HCC cell lines via sphingomyelin phosphodiesterase acid-like 3B (SMPDL3B)." (PMID 35565311, 2022).
diabetes (2 papers, 2019 to 2020). "In diabetes, it was postulated that, through the increased serum level of sphingomyelinase phosphodiesterase acid-like 3b (SMPDL3b), ceramide accumulates in the podocytes and contributes to podocytopenia." (PMID 32564139, 2020).
glomerular diseases (2 papers, 2020 to 2022). "Taken together, these studies imply that SMPDL3b is a potential therapeutic target for the treatment of kidney diseases, in particular of glomerular diseases." (PMID 35457062, 2022). "Studies suggest that SMPDL3b, S1P lyase, C1P, S1P and S1P receptors are valid and important targets for the development of novel therapeutic therapies for glomerular diseases." (PMID 32914148, 2020). "Nevertheless, SMPDL3b seems to be an attractive therapeutic target, at least for the treatment of glomerular diseases." (PMID 32914148, 2020). "The role of SMPDL3b in glomerular diseases will be discussed in detail in the section below." (PMID 32914148, 2020). "SMPDL3b is a GPI anchored lipid raft protein that was shown to have a role in glomerular diseases." (PMID 35457062, 2022).
myeloid leukemia (2 papers, 2021 to 2023). A clonal proliferation of myeloid cells and their precursors in the bone marrow, peripheral blood, and spleen. "SMPDL3B was expressed at significantly higher levels in almost all types of myeloid leukemia cells tested as compared to healthy bone marrow samples, whereas SMPDL3B was expressed at lower levels in lymphoid leukemia cells." (PMID 34504869, 2021). "Spearman’s rank tests showed that the mRNA expression of SMPDL3B was positively correlated with the mRNA expression of CD123, CD96, and CD25 in 151 AML patients, indicating that SMPDL3B may regulate myeloid leukemia development via promoting self-renewal of leukemia stem cells." (PMID 34504869, 2021).
non-alcoholic fatty liver disease (2 papers, 2021 to 2023). "Moreover, macrophage-derived thrombospondin 1 promotes obesity-associated non-alcoholic fatty liver disease through suppressing the expression of SMPDL3B." (PMID 34504869, 2021).
prostate carcinoma (2 papers, 2020 to 2023). A carcinoma that arises from epithelial cells of the prostate gland. "Nevertheless, that study also found, using TCGA data, that both progression-free survival and recurrence-free survival were lower in patients with prostate cancer with low SMPDL3B expression." (PMID 38813495, 2023). "The prostate cancer cells’ migration was inhibited by SMPDL3B." (PMID 38813495, 2023).
benign prostate hyperplasia (1 paper, 2020). "Therefore, SMPDL3B expression and its influence on clinical outcome was analyzed by real-time quantitative polymerase chain reaction (qRT-PCR) in two cohorts of patients with benign prostate hyperplasia (BPH), localized and locally advanced PCa." (PMID 32575490, 2020). "Two cohorts of patients with PCa who underwent radical prostatectomy (n = 40, n = 56) and benign prostate hyperplasia (BPH) controls (n = 8, n = 11) were profiled for SMPDL3B expression with qRT-PCR." (PMID 32575490, 2020).
gastric adenoma (1 paper, 2023). A neoplastic polyp that arises from the stomach. "By using clinical tissue samples and cell lines, the high expression of SMPDL3B was validated through the development of gastric adenoma cell lines that either overexpress or knockdown SMPDL3B." (PMID 38813495, 2023).
gastric cancer (1 paper, 2023). A primary or metastatic malignant neoplasm involving the stomach. "The elevated expression of SMPDL3B was linked to the infiltration of M2 macrophages in the gastric cancer microenvironment, which could be established using the TCGA database and clinical samples." (PMID 38813495, 2023). "Along with the normal gastric epithelial cell lines GES-1 and SGC-7901, the AGS, MGC-803, and MSN-45 human gastric cancer cell lines were used to confirm SMPDL3B expression." (PMID 38813495, 2023). "In contrast, the capacity of gastric cancer cells to invade was improved by overexpression of SMPDL3B." (PMID 38813495, 2023). "This study investigated more closely how SMPDL3B affects the ability of gastric cancer cells to migrate and invade." (PMID 38813495, 2023). "However, after overexpressing SMPDL3B, gastric cancer cells had improved migratory abilities and it was further demonstrated through a transwell invasion assay that SMPDL3B knockdown reduced the capacity of gastric cancer cells to invade." (PMID 38813495, 2023). "The normal gastric epithelial cell line GES-1 and the 4 gastric cancer cell lines SGC-7901, AGS, MGC-803, and MN-45 were found to express SMPDL3B mRNA and protein." (PMID 38813495, 2023).
Insulin resistance (1 paper, 2019). Increased resistance towards insulin, that is, diminished effectiveness of insulin in reducing blood glucose levels. "We previously observed that SMPDL3b is strongly upregulated in glomeruli of patients with insulin resistance and DKD3." (PMID 31217420, 2019). "It is possible that the increased ceramide generation in SMPDL3b overexpression cells still plays a key role in the induction of insulin resistance and that our failure to detect a change in ceramide content is linked to its rapid degradation and/or conversion to other substrates." (PMID 31217420, 2019).
invasive ductal carcinoma (1 paper, 2024). "SMPDL3B is a tumor suppressor gene, which when expressed at low mRNA gene expression levels has been associated with poor prognosis in invasive ductal carcinoma." (PMID 38672084, 2024).
leukemia (1 paper, 2021). A malignant (clonal) hematologic disorder, involving hematopoietic stem cells and characterized by the presence of primitive or atypical myeloid or lymphoid cells in the bone marrow and the blood. "Remarkably, the CCK-8 results indicated that knockdown of SMPDL3B expression could decrease the growth of each of those leukemia cell lines that express SMPDL3B." (PMID 34504869, 2021). "Since Kasumi-1 and THP-1 cells had the highest expression level of SMPDL3B of the cultured cells evaluated, we constructed SMPDL3B knockout Kasumi-1 and THP-1 leukemia cell lines via the CRISPR/Cas9 system and used these two cell lines in subsequent experiments." (PMID 34504869, 2021).
lymphoid leukemia (1 paper, 2021). A malignant lymphocytic neoplasm of B-cell or T-cell lineage involving primarily the bone marrow and the peripheral blood. "The transcription level of SMPDL3B was significantly elevated in AML patients compared to healthy control or lymphoid leukemia samples." (PMID 34504869, 2021).
Nephropathy (1 paper, 2018). A nonspecific term referring to disease or damage of the kidneys. "The development of xenograft nephropathy following XKTx appears to be closely associated with upregulation of CD80 and loss of SMPDL-3b in porcine podocytes." (PMID 29687010, 2018).
nephrotic syndrome (1 paper, 2022). A collection of symptoms that include severe edema, proteinuria, and hypoalbuminemia; it is indicative of renal dysfunction. "It was then proven that rituximab binds to sphingomyelin-phosphodiesterase-acid-like-3b (SMPDL-3b), acting as a direct modulator of podocyte function, leading to remission of the nephrotic syndrome." (PMID 36077163, 2022).
peritonitis (1 paper, 2019). Inflammation of the peritoneum (tissue that lines the abdominal wall and covers most of the organs in the abdomen). "In addition, Smpdl3b−/− mice displayed augmented responsiveness to TLR stimulation in peritonitis models." (PMID 30729183, 2019).
renal dysfunction (1 paper, 2025). "In conclusion, this study provides the first evidence that altered soluble SMPDL3B distribution is associated with subclinical renal dysfunction and metabolic abnormalities in ME." (PMID 41009450, 2025).
kidney diseases (6 papers, 2014 to 2022). "Rituximab was also shown to prevent Adriamycin-induced nephropathy in rats and radiation therapy was found to cause decreases in SMPDL3b protein expression and podocyte damage." (PMID 35457062, 2022). "Additionally, adriamycin-induced nephropathy in rats was associated with reduced expression of SMPDL3b, which was also prevented by rituximab." (PMID 32914148, 2020). "SMPDL3b is a glycosylphosphatidylinositol (GPI)anchored protein with reported roles in inflammatory processes and in kidney diseases." (PMID 32914148, 2020). "Recent studies identify SMPDL3b, GCS, S1P lyase and SK as key targets within sphingolipid metabolism for developing novel therapies against renal disorders." (PMID 29186855, 2017).
cancer (5 papers, 2014 to 2024). A tumor composed of atypical neoplastic, often pleomorphic cells that invade other tissues. "The present study initially addressed how pancancer analysis revealed SMPDL3B expression in several cancer types and focused on the analysis of TCGA-STAD data to conclude that SMPDL3B showed a tendency for high expression in GAC tissues." (PMID 38813495, 2023). "In the study, SMPDL3B overexpression or knockdown affected cancer cell growth and was investigated using the MTT cell proliferation assay." (PMID 38813495, 2023). "Further investigations are needed to uncover the prognostic significance of SMPDL3B in other types of cancers." (PMID 34504869, 2021). "Collectively, these findings call for further laboratory experiments and clinical trials to validate SMPDL3B in cancer progression." (PMID 34504869, 2021). "The prognostic importance of SMPDL3B in various cancer types will be revealed by future research." (PMID 38813495, 2023). "However, the potential role of SMPDL3B in human cancer, especially in AML, is still unknown." (PMID 34504869, 2021). "Among cancer and precancerous lesions glycoproteins, we further highlight seven glycoproteins found in high-grade dysplasia as well as cancer (IGHG1, CPA2, MYH2, AZU1, PRTN3, CA1, SMPDL3B), holding potential for non-invasive detection of aggressive traits." (PMID 38612533, 2024).